MIR374C (microRNA 374c)
Synonyms: hsa-mir-374c; mir-374c
Gene: MicroRNA gene on chromosome X (74,218,549 to 74,218,618, forward strand). Ensembl gene ENSG00000283534.
Gene Ontology:
Biological process: miRNA-mediated post-transcriptional gene silencing